GRID2 (glutamate ionotropic receptor delta type subunit 2)
Diseases named in the same sentence as GRID2 in open-access papers (continued):
Sharing a sentence is not in itself a finding about the gene and the disease.
hereditary cerebellar ataxia (1 paper, 2015). Cerebellar ataxia that is transmitted from parent to child. "Mutations in beta-3 spectrin influencing glutamate receptor GluRδ2 expression as well as deletions in the GRID2 gene itself have recently been discovered in SCA5 and other forms of hereditary cerebellar ataxia in humans." (PMID 26377085, 2015).
Hypertension (1 paper, 2013). The presence of chronic increased pressure in the systemic arterial system. "In addition, gene clusters anchored by TMEM16A, LPHN3 and GRID2 involved multiple neurotransmitter receptor genes contributing to the neuroactive ligand-receptor interaction pathway suggesting its possible link with hypertension." (PMID 23879630, 2013).
learning disability (1 paper, 2023). A group of disorders that affect a person's ability to learn or process specific types of information which is in contrast to his/her apparent level of intellect. "From our RNA-Seq data, among the 11 differentially regulated high-confidence ASD risk genes, there are few, which display learning disability phenotypes, which include GRIA1, GRID2, and IGF1." (PMID 37486945, 2023).
mastitis (1 paper, 2023). Inflammation of breast tissue during lactation or postpartum due to an obstructed duct or infection. "Another study reported association of GRID2 with conformation of the udder central suspensory ligament in cows; poor udder conformation is often related to incomplete milking, which increases the risk of mastitis and reduces milk production, thereby negatively affecting LP." (PMID 38075686, 2023).
psychotic disorder (1 paper, 2016). An abnormal condition of the mind that involves a loss of contact with reality. "Limited data from other studies provide support for the potential importance of GRID2 for familial phenotypes associated with psychotic disorders, as well as in response to drugs that act through glutamatergic mechanisms." (PMID 26905411, 2016).
seminoma (1 paper, 2025). A radiosensitive malignant germ cell tumor found in the testis (especially undescended), and extragonadal sites (anterior mediastinum and pineal gland). "Initially, the gene GRID2 had been identified as a gene of interest due to its associations with non-seminoma." (PMID 39809819, 2025).
speech disorder (1 paper, 2022). A term referring to disorders characterized by the disruption of normal speech. "In some other previously reported cases of patients with GRID2 mutations, speech disorders in patients were characterized by dysarthria without limits in speaking, or consisting of simple sentences." (PMID 35159210, 2022).
type 1 diabetes mellitus (1 paper, 2022). A chronic condition characterized by minimal or absent production of insulin by the pancreas. "Finally, the CPE gene was suggested to influence Type I diabetes mellitus whereas GRID2 and PTGDR are responsible for neuroactive ligand-receptor interaction." (PMID 36011330, 2022).
cancer (5 papers, 2010 to 2023). A tumor composed of atypical neoplastic, often pleomorphic cells that invade other tissues. "The PN association signal we found in intron 13 of GRID2 replicates across clinical trial arms and cancers." (PMID 37344884, 2023). "GRID2 has been noted as a large region of genomic instability (fragile site) and has been associated with cancer and neural development." (PMID 20487506, 2010).
tumor (3 papers, 2014 to 2025). "The upregulation of GRID2 can inhibit the invasion of tumor-associated immune cells." (PMID 41300831, 2025). "BIRC5 and HK2 showed higher expression in MYCN amplified cell lines and tumor tissues consistently, whereas GRID2 and RNASEL showed the opposite trends." (PMID 34746127, 2021). "Although the mutation in GRID2 was not seen in the primary tumor due to failure of the sequencing reactions, the mutation was confirmed in both metastatic samples." (PMID 24406431, 2014). "From the perspectives of tumor tissue and cell lines, we simultaneously found that BIRC5 and HK2 may increase tumor malignancy with MYCN amplification, whereas GRID2 and RNASEL were antagonistic to MYCN amplification." (PMID 34746127, 2021).
infection (1 paper, 2021). The state of being infected such as from the introduction of a foreign agent such as serum, vaccine, antigenic substance or organism. "Infection of GRID2 KO clones revealed that loss of GRID2 did not significantly impact viral replication kinetics in MDBK cells." (PMID 34834954, 2021).
neurological disease (1 paper, 2024). "Here we present a comprehensive description of GRID1 and GRID2 variants that have been reported in individuals with neurological disorders, in addition to a number of newly described variants." (PMID 37944084, 2024). "Evidence in mice and humans also suggests that missense variation in GRID2 is involved in neurological disease pathogenesis." (PMID 37944084, 2024).
peripheral neuropathy (1 paper, 2023). A disorder affecting the peripheral nervous system. "We identified a locus consisting of low-frequency variants in intron 13 of GRID2 associated with time-to-onset of first peripheral neuropathy (PN) indexed by rs17020773 (p = 2.03 × 10−8, all patients, p = 6.36 × 10−9, taxane treated)." (PMID 37344884, 2023).
GRID2 also shares sentences with these, for which no sentence is quoted: cerebellar ataxia (10 papers); Cerebellar atrophy (4); developmental delay (3); prostate carcinoma (3); endometrial carcinoma (2); Intellectual disability (2); obsessive-compulsive disorder (2); Tremor (2); atherosclerosis (1); Brain atrophy (1); breast carcinoma (1); ciliopathies (1); Duchenne muscular dystrophy (1); dwarfism (1); encephalitis (1); Episodic Ataxia (1); frontotemporal dementia (1); Huntington disease (1); neurodevelopmental disorder (1); Nystagmus (1); Oculomotor apraxia (1); osteosarcoma (1); primary effusion lymphoma (1); psychiatric diseases (1); Spastic paraplegia (1); Spinocerebellar ataxia autosomal recessive 18 (1); teratozoospermia (1); Tourette syndrome (1); viral infection (1).